FGFR2 (fibroblast growth factor receptor 2)
Diseases named in the same sentence as FGFR2 in open-access papers (continued):
Sharing a sentence is not in itself a finding about the gene and the disease.
tumor (continued). "Thus, FGFR1 is expressed in both core and invasive areas of xenografted human GBM and FGFR2 is mainly expressed in the tumor core." (PMID 37579831, 2023). "Thus, we proposed that in neighbor PanCK(+) tumor epithelial cells, FGFR2 is a potential receptor that binds to FGF20." (PMID 37964075, 2023). "As molecularly guided treatment has been increasingly used to combat the heterogeneous tumour microenvironment of CCA, targeted therapies, such as ivosidenib for patients with IDH1 mutations and pemigatinib for patients harbouring FGFR2 fusions, respectively, have been approved for use in CCA." (PMID 37173994, 2023). "We detected FGFR2-amplified tumor cells in 4 of 29 primary tumors." (PMID 36416959, 2023). "Furthermore, a patient diagnosed with urothelial cancer with FGFR2 amplification had a confirmed PR (35% tumor reduction) and completed 40 weeks of treatment." (PMID 37681152, 2023). "Our demonstration that mutant FGFR2 enhances the sensitivity to FGF7‐induced ADAM17 activity provides an explanation of how these tumours might adapt in an environment with reduced growth factors." (PMID 37165578, 2023). "Homogeneous FGFR2 amplification in tumors of the upper GIT is the exception." (PMID 36416959, 2023). "Variable expression and splicing of FGFR2 isoforms may promote tumor progression under the mechanism of EMT." (PMID 38269250, 2023). "We found that CEBPB and FGFR2 were differentially elevated in the organoids and bile duct cells of CC patients and HB tumor region, and that elevated expression of FGFR2 and CEBPB may contribute to malignant transformation of CC." (PMID 36996081, 2023). "Notably, the percentage of FGFR2-immuno-positive bile duct cells in CC liver was also higher than that of HB non-tumor." (PMID 36996081, 2023). "The efficacy of checkpoint inhibitors may also correlate with expression of FGFR2, especially in the tumor microenvironment." (PMID 38155920, 2023). "Deregulation of FGFR2-driven signalling may result in impaired ductal branching and disabled development of mammary gland during morphogenesis, as well as tumour formation and further progression of the disease in adults." (PMID 37191822, 2023). "Collectively, these findings suggest that FGFR2 amplification may play an important role in tumor progression in GC, particularly in lymphatic metastasis." (PMID 37510761, 2023). "Finally, we verified TAX evidently inhibited the tumor growth in nude mice and decreased the expression of c-Myc, cyclin D1, p-AKT and FGFR2 in xenograft tumor." (PMID 37567936, 2023). "Genes selected based on their log2FoldChange values for RT-qPCR verification in 31 CC and 11 HB non-tumor liver tissues revealed significantly elevated expression of FGFR2 in 7 and CEBPB in 2 CC liver tissues (CC vs HB: 4.082 vs. 0.7671, p<0.01; 2.506 vs. 1.210, p<0.01)." (PMID 36996081, 2023). "Additionally, FGFR2 mean fluorescence intensity was significantly higher in tumor core areas compared to invasive areas." (PMID 37579831, 2023). "EMT tumor 222 had a similarly bounded focal amplification event over FGFR2 and ATE1 that increased both gene copy numbers by 1, but EMT tumor 1356 has an estimated copy number gain of 471 over this region and correlates well with gene expression levels of FGFR2." (PMID 37805590, 2023). "Since ESRPs-mediated FGFR2 alternative splicing has been shown to alter macrophage polarization in non-tumor models, we thus examined whether the phenotype of TAMs in these ESRPs-treated mice could be altered." (PMID 37090731, 2023).
tumor (continued). "Agents acting on tumor-specific oncogenes in BTC may target fibroblast growth factor receptor 2 (FGFR2), isocitrate dehydrogenase (IDH), B-raf kinase (BRAF), and human epidermal growth factor receptor 2 (HER-2)." (PMID 37046766, 2023). "FGFR2 positively regulates PD‐L1 and helps tumor cells undergo immune escape." (PMID 37750089, 2023). "Dysregulation of FGFR2 may play a role in oncogenesis through angiogenesis and the migration and survival of tumor cells." (PMID 37895447, 2023). "In light of our previous findings, indicating a possible oncogenic role of the mesenchymal isoform of FGFR2 (FGFR2c) aberrantly expressed in AK keratinocytes, we analyzed the possible tumor-promoting role of this receptor in the stromal AK counterpart in this work." (PMID 36979155, 2023). "Furthermore, we demonstrated that there are discrepancies between the amplification status of the primary tumor and the corresponding lymph node metastases, which can be explained by intratumoral heterogeneity of FGFR2-amplified tumor clones." (PMID 36416959, 2023). "Hypothetically, the use of circulating tumor DNA (ctDNA) could improve the results of FGFR2 molecular testing." (PMID 38155920, 2023). "We demonstrated that the activation of Fgfr2 signaling could initiate tumor formation by suppressing Brca1 via the ERK-YY1 axis." (PMID 37063417, 2023). "Aprutumab ixadotin binds to FGFR2 and then selectively induces cell death, through an unknown mechanism of action, in FGFR2-expressing tumor cells." (PMID 37454027, 2023). "Because ADAM17 is the subsequent step following FGFR2 activation in migration and proliferation of EM cells, targeting ADAM17 function in FGFR2‐mutant EC cells may have a beneficial effect in tumour suppression." (PMID 37165578, 2023). "However, very recently it has been reported that FGFR2 can be expressed also in ER/PR-positive tumours where, surprisingly, low FGFR2 expression correlates with poor prognosis." (PMID 35193394, 2022). "In this case, treatment with FGFR2 and Met inhibitors blocked the tumor growth." (PMID 35954414, 2022). "Indeed, in a human TNBC xenograft model, single-dose FGFR2-TTC reduced tumor growth and was well tolerated." (PMID 36726355, 2022). "All these data suggest that FGFR2+ fibrocytes simultaneously gain the abilities of ECM production and stroma construction; enhance the interactions with other cells in tumor mass and activate differentiation associated signaling pathways, such as Hippo pathway, upon differentiation into CAFs." (PMID 35941662, 2022). "However, further experiments to genetically ablate FGF7 and FGFR2 in tumor xenografts are needed to confirm the proliferative role of this signaling axis in vivo." (PMID 34850536, 2022). "Interestingly, three GC patients with concurrent FGFR2 amplification and FGFR2 fusion (3/7 cases, 42.8%) had FGFR2 protein overexpression in their tumor." (PMID 35342406, 2022). "In support of this, single-dose FGFR2-TTC inhibited tumor growth in a xenograft model of CRC." (PMID 36726355, 2022). "In all, 28 patients (N = 28, 2.0%) had FGFR2 aberrations detected in their tumor by NGS panel." (PMID 35342406, 2022). "Six patients (28.5%) had over 50 copies of FGFR2 in their tumor specimens." (PMID 35342406, 2022). "Furthermore, FGFR2 immunostaining was found at the invasion front of the tumor in 2.5% (6 cases), toward the gastric lumen in 19.4% (47 cases), and at the tumor center in 79.1% (189 cases) of the cases." (PMID 35167603, 2022). "It is particularly noteworthy that 6 chemokine receptors in GO term “chemokine binding”, including CXCR4, CCR5, CCR1, CCRL2, CMKLR1 and A2M, are specific expressed in FGFR2+ fibrocytes before arriving in tumor sites suggesting their possible roles in fibrocyte recruitment." (PMID 35941662, 2022).
tumor (continued). "But implantation with KYSE30 could significantly increase FGFR2+ BM cells, which was rapidly decreased to basal level after tumor removal, indicating that FGFR2+ cells in BM could be mobilized by active tumors." (PMID 35941662, 2022). "Interestingly, tumours with overexpression of E18-truncated FGFR2E18-C3 responded particularly well to FGFR2 targeting." (PMID 35948633, 2022). "Proteomic analyses of tumours induced by Fgfr2 variants demonstrated consistent expression and phosphorylation of FGFR2 variants along with downstream signalling activities, which were distinct from the phosphoproteome of FGFR2-independent K14-cre;Brca1F/F;Trp53F/F;(Mdr1a/b−/−) tumours." (PMID 35948633, 2022). "However, we show that the biological significance of FGFR2 is a function of tumor type according to the Lauren type." (PMID 35167603, 2022). "Our study demonstrates for the first time that the role of FGFR2 in ER+ BCa is dependent on the hormonal background of the tumour and relies on the involvement of the FGF7/FGFR2➔JunB axis in the regulation of PR modulatory effects on ER‐associated cellular events." (PMID 35726195, 2022). "FGFR2 status was correlated with the Laurén phenotype and tumor grade." (PMID 35167603, 2022). "Expression levels of seven CBX7 targets, namely Wnt10a, Ccne1, Fgfr2, Bhlhe22, Klhdc8a, Pde10a, and Dusp4, which had been significantly inhibited in miR-181ab1 KO compared to WT tumours in mice, were also significantly lower in either iClust2 or iClust3 than iClust1 HCCs." (PMID 35867177, 2022). "The missense variant of FGFR2 (c.2211G>T, p.(Met737Ile)) with no clinical significance in the ClinVar database was detected in one tumor (M-6)." (PMID 36142417, 2022). "Of note, 8 (0.6%) patients had both FGFR2 amplification and FGFR2 fusion in their tumor specimen." (PMID 35342406, 2022). "Likewise, FGFR2 fusions were detected in the primary tumor and cfDNA in 8 of 12 (67%) patients prior to BGJ398 treatment (NCT02150967)." (PMID 35402233, 2022). "Fgfr2 activation created an immunosuppressive environment and enhanced tumor progression." (PMID 35547739, 2022). "Our next question is how FGFR2+ fibrocytes are recruited into tumor sites." (PMID 35941662, 2022). "However, in individual tumor samples, FGFR2 and FGFR3 expression levels were enhanced: fold-changes > 2 were observed in 5 (12.5%) and 7 (17.5%) samples, respectively." (PMID 36142417, 2022). "The effects of splicing are most relevant to FGFR2; expression of the FGFR2b splice isoform can restore apoptotic sensitivity to cancer cells, whereas switching to FGFR2c may drive tumor progression by triggering epithelial-mesenchymal transition." (PMID 34007277, 2021). "FGFR2 CNVs with FGFR2 mRNA expression were compared across all TCGA tumor types." (PMID 33968743, 2021). "Moreover, mice bearing Fgfr2 activation display inflammation, PD‐L1 upregulation, and tumor induction." (PMID 34514747, 2021). "Notably, specific inhibitors of FGFR2 verified that the tumor-derived organoids were indeed reliant on the pathway, providing a rationale for the molecular targeted therapy against FGFR2-driven iCCA." (PMID 34064809, 2021). "Accordingly, downregulation of FGFR2 in MFM-223 tumor limits FGFR2-dependent activation of HER3." (PMID 34900714, 2021). "The most robust data on anti-tumour activity and efficacy have been generated from trials using pan-FGFR inhibitors—specifically, trials in urothelial cancers with FGFR3 mutations and iCCA with FGFR2 fusions." (PMID 33268819, 2021). "In addition, when FGFR2 was downregulated using shRNAs, the population of tumor-initiating cells was also significantly downregulated." (PMID 33535617, 2021). "These disparate tumor trajectories show how the proapoptotic function of FGFR2 may be converted to tumorigenicity by a variety of epistatic suppressor gene defects." (PMID 34007277, 2021).
tumor (continued). "In addition, more transcripts of “Cell proliferation of carcinoma cell line” (z = 1.13, p = 1.5 × 10−6) and “Neoplasia of cancer cells” (z = 1.13, p = 2.22 × 10−4) categories, such as Fgfr2 and Nek2, were detected." (PMID 34099670, 2021). "Gene and protein expression levels, such as Fgfr2 and αSMA, were different between peripheral and perihilar tumors, showing that characteristics of tumors generated by the same technique can differ depending on the tumor location." (PMID 34282753, 2021). "Through FISH testing, FGFR2 translocations were identified in nine (5.2%) tumor specimens." (PMID 33692336, 2021). "Derazantinib also showed strong tumor inhibition in FGFR2 fusion-driven tumor xenograft models." (PMID 34732230, 2021). "In this study, we tried to develop novel PDCs with high affinity for FGFR2 for tumor treatment." (PMID 34440055, 2021). "Moreover, low FGFR2 was also associated with prognostically unfavorable tumor characteristics, i.e., high proliferation index and poor differentiation, which may suggest that in certain biological settings, tumor aggressiveness might be featured or enforced by low FGFR2." (PMID 32971804, 2020). "However, in our study nuclear localization of FGFR2 was observed in both male and female tumour species." (PMID 32522271, 2020). "To investigate the activities of DcP5 and P5 on the RTK‐signaling pathways, which are the downstream pathways of FGFR2, we performed Western blot analysis on tumor cells and normal cells surrounding the tumor to evaluate the phosphorylated FGFR2, AKT, and ERK1/2." (PMID 34766128, 2020). "Given that FGFR2 was overexpressed in IM-resistant GIST T-1R cells, we sought to examine whether the knockdown of FGFR2 will sensitize tumor cells to DNA-topoisomerase II inhibitors due to attenuation of HR-mediated DNA repair." (PMID 31948066, 2020). "Nuclear expression of FGFR2 was observed in both female and male tumour specimens." (PMID 32522271, 2020). "Moreover they showed that circulating tumor DNA from 34 patients progressing to the CDK4/6 drugs had amplifications or activating mutations of FGFR1 and FGFR2, which were as high as 41% in the patients." (PMID 32188012, 2020). "Besides the 12 FGFR2 fusions, a single FGFR3-TACC3 fusion product was detected in a fluke-associated CCA tumor." (PMID 32315234, 2020). "Moreover, FGFR2 mutations have been reported in a diverse range of cancer types including BC, and FGFR inhibitors reported to have a direct anti-tumor effect on cancer cells." (PMID 33112566, 2020). "In addition, nintedanib was recently shown to exert direct anti-tumor effect on tumor cells, but only those with oncogene addiction to growth factors receptors targeted by nintedanib, such as PDGFRα, FGFR2, FLT3, or RET." (PMID 32133285, 2020). "The following tumor mutations were reported in patients with clinical benefit: cKIT (n = 1), CSF-1R (n = 1), PDGFRα (n = 2), PDGFRβ (n = 1), VEGFR1 (n = 1), VEGFR2 (n = 2), FLT3 (n = 1), FGFR2 (n = 2), RET (n = 1), and TrkA (n = 1)." (PMID 32292573, 2020). "The four epithelial tumor clusters showed patient-specific tumor characteristics (high FGFR2 or MET) and intratumoral heterogeneity in gene expression signatures of cancer-related processes, such as cell proliferation, stemness, TGF-β signaling in EMT, hypoxia, and angiogenesis." (PMID 33277616, 2020). "Accordingly, molecular profiling of CCA tumours has become increasingly significant over the past few years due to the identification of potentially druggable molecular alterations, such as mutations in IDH1/2 and FGFR2 fusions." (PMID 32694694, 2020). "Furthermore, FGFR2-Fc significantly suppressed FGF2-induced tube formation in a HUVEC sandwich tube formation assay in which HUVECs were co-cultured with FGFR2-Fc–expressing tumor cells." (PMID 32076044, 2020). "Increased FGFR2 expression in HCC has been correlated with decreased tumor differentiation." (PMID 31940413, 2020).
tumor (continued). "The better prognosis was observed in fluke negative tumours harbouring FGFR2 fusions or IDH mutations." (PMID 32932925, 2020). "Lenvatinib, a multiple tyrosine kinase inhibitor including VEGFR and FGFR inhibition, showed marked antitumor activity against VEGFR2-Fc–expressing resistant tumors accompanied with a decrease in the area of tumor vessels and suppression of phospho-FGFR2 in tumors." (PMID 32076044, 2020). "We observed a high variability in FGFR2 expression between the different tumour samples." (PMID 32522271, 2020). "In this study, we addressed a role of FGFR2 in tumor response to hypoxic challenge." (PMID 30837551, 2019). "Furthermore, in ccRCC, FGFR2-IIIc expression was found to be correlated with higher tumor grade and worse prognosis." (PMID 31881796, 2019). "To understand whether FGFR2 and ESRP1 overexpression was associated with increased CN, we analyzed TvsN and unpaired tumor samples from cohort #1 dataset #8 and #9." (PMID 31881796, 2019). "In conclusion, derazantinib monotherapy demonstrated a favourable safety profile at a dose of 300 mg daily with promising anti-tumour activity in a selected patient population of iCCA with FGFR2 gene fusion following disease progression on first-line systemic chemotherapy." (PMID 30420614, 2019). "Altogether, these studies revealed that FGFR2-IIIb isoform may have both oncogenic and tumor-suppressive effects in a tissue-dependent manner." (PMID 31881796, 2019). "FGFR TK family (FGFR1, FGFR2, FGFR3, and FGFR4) members encode transmembrane proteins that contain immunoglobulin-like and kinase domains that play diverse roles in controlling cell proliferation, cell differentiation, angiogenesis, and tumor development." (PMID 31007851, 2019). "Immunolabeling of FGFR-2, a member of the fibroblast growth factor receptor family, showed a predominantly intermediate or strong expression in the cytoplasm of the tumor cells highlighting the fibrillary processes of the astrocytic differentiated tumor cells." (PMID 30894200, 2019). "Consistent with the role of ΔNp63α as a regulator of FGFR2, further analyses revealed the fibroblast growth factor (FGF) signaling pathway, specifically FGFR2, was shown to be significantly upregulated by ΔNp63α and required for tumor progression to occur in this model." (PMID 31340447, 2019). "These genetic alterations involving BRAF, KRAS, RAF1, NF1, FGFR1, and FGFR2 were mutually exclusive (i.e. no tumor harbored any two of these variants simultaneously)." (PMID 29880043, 2018). "Amplification of PIK3CA and FGFR2 might contribute to acquisition of radioresistance by the tumor in the present study." (PMID 30220971, 2018). "The conjugate delivered MMAE selectively to FGFR2-positive tumor cells." (PMID 29420662, 2018). "FGF1 stimulation could remarkably increase tumour invasion with normal FGFR2 expression, but the invasion of RBE or HuCCT‐1 was decreased when FGFR2 was knocked down and increased when SPRY2 was knocked down." (PMID 30160357, 2018). "With wound healing assay, we proved that FGFR2 knockdown notably impaired the tumour cell migration while silencing SPRY2 could promote migration of RBE or HuCCT‐1 cells." (PMID 30160357, 2018). "In addition, amplification of PIK3CA and FGFR2 in T2 and T3, combined with activating mutations in KRAS and PIK3CA in T1−3, indicates a critical role for the RAS-PI3K axis in tumor survival through multiple rounds of radiotherapy." (PMID 30220971, 2018). "We demonstrate that Vegfr2 gene dosage, but not synergy with endothelial Fgfr1 and Fgfr2, is critical for tumor growth and associated tumor angiogenesis." (PMID 30283071, 2018). "According to several studies, FGFR2 amplifications-shown to occur in 4% of TNBC, as well as activating mutations of the receptor-have been associated with high sensitivity to FGFR inhibitors and maintenance of tumor-initiating cells." (PMID 30011957, 2018). "FISH also revealed a striking amplification of FGFR2 in tumor-involved tissue." (PMID 28835367, 2017).